LOXL2 (lysyl oxidase like 2)
Diseases named in the same sentence as LOXL2 in open-access papers (continued):
Sharing a sentence is not in itself a finding about the gene and the disease.
cancer (continued). "Differential gene expression and gene ranking analyses revealed that the expression of CD74, HLA-DRA, HLA-DRB1, and FXYD3 was elevated in MHC-II+ cancer cells, whereas the expression of LOXL2 and DLL4 was increased in MHC-II− cancer cells." (PMID 41281745, 2025). "Concerning cancer cell lines, the expression of LOX, LOXL1, LOXL2, LOXL3 and LOXL4 was highest in GBM, GBM, GBM, SKCM and PAAD, while lowest in CLL, CLL, LCML, DLBC and CLL, respectively." (PMID 40179101, 2025). "Our findings indicated a significant relationship between LOXL2 expression and the majority of the genes in immune checkpoint pathways, like VEGFA, CD276, TGFB1, and IL10 in pan-cancer." (PMID 38922489, 2024). "LOXL2 expression was correlated with DSS in various cancers, including LUAD, GBMLGG, and other 15 types of cancer." (PMID 38922489, 2024). "LOXL2 catalyses the cross‐linkage of extracellular collagen to change the stiffness of the ECM, facilitating the motility of cancer cells." (PMID 37753805, 2023). "Taken together, we propose a schematic model in which the LCN2/LOXL2/MMP9 complex promotes the migration and invasion of cancer cells through intracellular and extracellular means." (PMID 37753805, 2023). "In agreement with our results, all the studies showed that ZEB1‐circRNAs are upregulated in cancer; however, they identified different targets and functional axes (miR‐337‐3p/TGFBR1, mR‐195‐5p/LOXL2, miR‐448/EEF2K, miR‐200a‐3p/CDK6 and miR‐199a‐3p/PIK3CA)." (PMID 37408496, 2023). "LOXL2 belongs to the lysyl oxidase (LOX) family and increasing evidence has shown its role in cancer cell invasion and metastasis." (PMID 37583701, 2023). "We started by characterizing the basal level of Cu-dependent proteins which are reported to play a role in cancer development and spreading (i.e., ATP7A, LOXL2, CCS and Cytochrome c Oxidase) in the cells under study." (PMID 36454513, 2023). "Expression of the CD326 gene and protein (EPCAM), a representative surface marker of cancer stemness, was reduced, and it was found through flow cytometry that CD326 positive cells were decreased by LOXL2." (PMID 37737908, 2023). "We further identified multiple cancer-relevant target genes of the Zn2+-activated ZEB1, among which LOXL1 and LOXL2, in particular, function as pioneer factors for invasiveness." (PMID 36910659, 2023). "Taken together, LCN2, LOXL2, and MMP9 are highly expressed in ESCC, and are emerging as promising therapeutic targets in many types of cancer." (PMID 37753805, 2023). "A monoclonal antibody (AB0023) targeting LOXL2 inhibits stoma generation and TGF-β activation in cancer and shows more efficacy and safety than BANP." (PMID 36906534, 2023). "Previous studies have demonstrated that, contrarily to LOXL2, LOXL4 overexpression has an inhibitory effect on cancer proliferation and progression-related events in different cancer models." (PMID 35800439, 2022). "Each cancer analyzed had a positive slope above 0.2 and had a correlation between OSMR and LOXL2 mRNA expression." (PMID 34011405, 2021). "The present suggests the feasibility of targeting the LOXL2-HIF1a feedback loop to inhibit aerobic glycolysis and to reverse the malignancy of PDAC, a cancer type for which existing therapeutic options are clinically insufficient." (PMID 34836938, 2021). "LOX family members (LOX, LOXL1, LOXL2, LOXL3, LOXL4) reportedly mediate cell migration and metastasis of different cancers." (PMID 34815382, 2021). "Further, both LOXL2 depletion and treatment of TNBC with chromatin-modifying drugs sensitized cancer cells to conventional treatments." (PMID 31462706, 2020). "The transcription factor Snail1, together with LOXL2, would participate in downregulating the CDH1 gene and other heterochromatin transcripts, giving rise to transformation of cancer epithelial cells into mesenchymal cells (through EMT)." (PMID 31462706, 2020).
cancer (continued). "For example, LOX, LOXL2, LOXL3, and LOXL4 are overexpressed in more invasive cancers, such as triple negative breast cancers, inducing cancer cell invasion and metastasis." (PMID 32984031, 2020). "Furthermore, LOXL2, as a copper-dependent enzyme, could be inhibited by copper chelation agents, such as penicillamine, trientine, disulfiram, clioquinol, or tetrathiomolybdate (TM), which could be used in cancer treatment." (PMID 32211324, 2020). "And most of the 24 DEPs (CDK1, SFN, PRKAR2B, MKI67 and MDK involved in the cell cycle; LOXL2, P4HA1, P4HA2, SPRX, DES, PRPH and CALML3 involved in construction and regulation of extracellular matrix; IL33 and EHD3 may involve in immune) were linked to cancer hallmarks." (PMID 33200655, 2020). "LOX, LOXL1, and LOXL2 were upregulated in certain kinds of cancers, and only LOX and LOXL2 were significantly elevated in RCC." (PMID 32970930, 2020). "It was reported that overexpression of LOXL2 drove EMT via upregulating the expression of SNAIL (SNAI1/2), ZEB (ZEB1/2) via IRE1-XBP1 signaling pathway or FAK/SRC signaling pathway in cancer cells." (PMID 32211324, 2020). "Inhibiting LOX and lysyl oxidase-like 2 (LOXL2) and LOXL4 decreased metastasis in several cancer cell types." (PMID 29896451, 2018). "Futhermore, this study revealed the targets genes of LOXL2 in HCC cells and provide molecular basis of cancer cell-derived LOXL2 functioning with the hypoxia-mimetic agent CoCl2." (PMID 28449718, 2017). "We investigated the correlation between LOXL2 expression levels and CRC metastasis rate in patients, by immunohistochemically (IHC) examining LOXL2 expression in cancer tissue samples obtained from CRC patients." (PMID 29113306, 2017). "In the first one, the localization of endogenous LOXL2 in MDA-MB-231 and Hs578T basal-like carcinoma cell lines expressing high levels of LOXL216 was analysed by Optiprep gradient centrifugation and confocal immunofluorescence." (PMID 28332555, 2017). "In RCC cells, miR-29b directly suppresses the lysyl oxidase-like 2 (LOXL2) gene, leading to inhibition of cancer cell invasion." (PMID 27487138, 2016). "In previous studies, intracellular functions of LOXL2 have been postulated relating to the promotion of EMT and the invasiveness of cancer cells." (PMID 27285767, 2016). "With the exception of LOXL2, the RAS target genes that play a role in cancer invasion and metastasis are downregulated in the weak oscillators, thus being associated with the bad prognosis phenotype." (PMID 24875049, 2014). "Among those genes are IFNGR2, PITX2, RFWD2, PPARγ, LOXL2, Rab6 and SPARC, all involved in cancer-related pathways." (PMID 24875049, 2014). "LOXL2-driven ECM accumulation and fibrosis may strengthen the solid tumor microenvironment and act as a chemotactic factor that promotes cancer cell invasion and migration." (PMID 41399365, 2026). "However, CA9 was dominating in the cancer cell lines, whereas LOX and LOXL2 were dominating in the fibroblasts." (PMID 39011470, 2024). "However, increased expression of miR-29a hinders the spread of cancer cells to other parts of the body by targeting VEGFA, LOXL2, and LOX." (PMID 38915826, 2024). "In preclinical cancer models, inhibiting LOXL2 does result in a reduction in metastasis but not in reduced primary tumor size." (PMID 38659022, 2024). "For instance, the expression of LOXL2 (Lysyl Oxidase Like 2) is the negative prognostic biomarker for many cancers." (PMID 39329988, 2024). "Each successive layer expresses additional cancer marker genes – considering top-1 markers, coexpression hotspot 0 (CH0) expresses DEGS2; CH2 expresses BRINP3; CH10 expresses SUSD3; and CH19 expresses LOXL2." (PMID 37848426, 2023). "Although not related to the cancer field, it is worth mentioning that in a cell model of hypertrophic flavum ligamentum, LOXL2 mRNA is targeted by miR-4731, and LOXL2 downregulation is relieved by circPDK1." (PMID 37762708, 2023).
cancer (continued). "Therefore, LOXL2, UBE2D1, UBE2D3, and DβH can be considered as potential candidates for cancer diagnosis, prognosis, and therapeutic biomarkers." (PMID 37886979, 2023). "The recent discoveries of different activities of LOXL2 and LOXL2 actions independent of its oxidative deamination catalytic activity in cancer have opened the way for novel therapeutic approaches." (PMID 37762708, 2023). "Next, we analyzed a broader cancer cell panel to determine whether there was a consistent inverse correlation between BRD4 and LOXL2 expression." (PMID 37937685, 2023). "LOXL2 belonging to the LOX family, has the typical function of catalyzing the cross-link of elastin and collagen in the ECM and has attracted much attention in cancer biology." (PMID 36185284, 2022). "The lysyl oxidase-like 2 (LOXL2) is a protein that catalyzes the cross-linking of collagen and elastin components in the ECM and has been reported to contribute to the development and progression of several cancer types." (PMID 34900673, 2021). "In addition, in cancer tissues, the expression and area of COL I, COL I/COL III, and COL I area/COL III area and the expression of LOX and LOXL2 in patients with cold constitution were significantly higher than those in patients with heat constitution." (PMID 34335820, 2021). "Similarly, the expression of the four MPM biomarker candidates LOX, LOXL1, LOXL2 and ZFPM2 were shown to be significantly increased in the MPM tissues when compared to the non-cancer patient samples." (PMID 31921422, 2020). "LOXL2, E‐cadherin, and MMP2/9 are involved in cancer cell invasion and metastasis." (PMID 31162697, 2020). "Research regarding the functions of LOXL2 and STC1 in cancer development is limited." (PMID 32139696, 2020). "Although miRNAs in LOXL2 regulation have not been studied in CVDs, evidence from cancer studies have shown that miRNAs can regulate LOXL2 expression in tumors." (PMID 32824630, 2020). "Integrative analyses of LOXL2 expression were conducted in three GEO expression profile datasets (i.e., GSE63514, GSE7803, and GSE9750), which included transcriptomic profiles of normal cervix and primary cancer tissue." (PMID 32211324, 2020). "Lysyl oxidase-like 2 (LOXL2) is a copper-dependent monoamine oxidase that contributes to the remodelling of the extracellular matrix (ECM) by cross linkage of collagen and elastin fibres and has emerged as a potential therapeutic target in cancer and fibrosis." (PMID 29953488, 2018). "Our recent studies of lung SCC revealed that miR-1/miR-133a clustered miRNAs, miR-206 and the miR-29-family inhibited cancer cell migration and invasion through targeting of several oncogenic genes, such as coronin-1C (CORO1C), c-MET and lysyl oxidase like 2 (LOXL2)." (PMID 27765924, 2016). "Here we demonstrate that LOXL2, beyond its extracellular function as inducer of desmoplastic stroma and its intracellular function as an inducer of EMT and cancer cell invasion, can also endow DTC with CSC–like properties thus mediating their emergence from dormancy to proliferative growth." (PMID 27655685, 2016). "LOXL2 induces EMT by stabilizing Snail, a suppressor of CDH1 in carcinoma progression." (PMID 27285767, 2016). "It has been demonstrated that a LOXL2 isoform produced due to lack of exon 13 (LOXL2 Δe13) modulates cancer cell migration and invasion through a different mechanism from that of full-length LOXL2." (PMID 26273588, 2015). "Besides, the pathological effects and function of LOXL2 are underrecognized, and systematic pan-cancer analysis for LOXL2 is still lacking." (PMID 38922489, 2024). "Later cancer trials dosed patients with 700 mg for 3–6 month periods; however, these trials recruited patients irrespective of LOXL2 expression, activity or presence of fibrosis, which may have diluted efficacious responses to Simtuzumab." (PMID 35205728, 2022).
cancer (continued). "Besides VEGFA, the inhibition of miR-29b could upregulate the expression of other oncoproteins, such as DNMT3b, LOXL2, and MMP2 in some cancers." (PMID 34306080, 2021). "Two of the 16 positively regulated genes, ERO1L and LOXL2, are involved in vascular endothelial growth factor (VEGF) secretion and extracellular matrix (ECM) remodeling, respectively, suggesting KDM4B is essential for the general malignant phenotypes that are shared by multiple cancers." (PMID 34766154, 2021). "The participation of LOXL2 in collagen maturation and the ability of SW480 cells to remodel ECM, as demonstrated in our above experiments, make it possible to consider it as an important participant in the formation of the border collagen structure typical of cancers." (PMID 33143259, 2020). "Though LOXL-e13-DEG was not annotated by such terms related to the malignant degree of tumors, it could not be excluded that LOXL2-e13 also plays important roles in carcinoma development." (PMID 25254241, 2014). "This concept has many prospects: the ability to confer a molecule high specificity and selectivity for the cancer without affecting normal tissues, development of high affinity binders, and using different specificities of LOXL2 targeting antibodies to alter the outcome." (PMID 23125850, 2012). "However, at least three genes induced in the fibroblast serum response, PLAUR, LOXL2, and MIF, have been previously shown to increase cancer invasiveness or angiogenesis in animal xenograft models; each of these three genes has also been shown to play an important role in wound healing." (PMID 14737219, 2004). "Additionally, it should be considered that small-molecular-weight LOXL2 inhibitors are designed to block the catalytic activity of the enzyme, and we know that the classical oxidase activity is not required for many of the intracellular functions of LOXL2 in cancer, such as the induction of EMT." (PMID 37298909, 2023). "The mechanism of LOXL2 regulation in the cell invasion, metastasis and EMT in different cancers is still not very clear." (PMID 41281746, 2025). "Hypoxic cell-derived sEVs delivered high amounts of LOXL2 to non-hypoxic HNSCC cells to elicit epithelial-to-mesenchymal transition (EMT) and induce the invasion of the recipient cancer cells." (PMID 34646366, 2021). "Since FAK responds to extracellular stimuli, including signals from the extracellular matrix (ECM), it is not surprising that wild-type LOXL2, an ECM remodeling enzyme, activates the FAK signaling pathway as has been reported in both gastric and basal-like carcinoma cells." (PMID 24414204, 2014). "In ovarian granulosa cells, LOXL2 is phosphorylated by the large tumour suppressor kinase 1 (LATS1), a negative regulator of YAP in the Hippo signalling pathway, although the consequences of this phosphorylation in the context of cancer have not yet been analysed." (PMID 37762708, 2023).
cardiovascular diseases (8 papers, 2017 to 2023). "Understanding mechanisms of developmental remodeling and identification of time‐specific intervention, for example, via targeting LOXL2, in this vulnerable population will ensure prevention of early development of cardiovascular disease." (PMID 37038896, 2023). "Lysyl oxidase-like 2 (LOXL2) has been identified as an essential mediator of extracellular matrix (ECM) remodeling in several disease processes including cardiovascular disease." (PMID 37029269, 2023). "This work is the first to demonstrate that the reduction of Loxl2 has a protective mechanism in the Drosophila heart and extends mean lifespan, consistent with Loxl2’s role in mammalian cardiovascular disease." (PMID 34734976, 2022). "There is, however, a paucity of available literature, thus hindering efforts to fully elucidate not only the exact mechanisms by which LOXL2 signaling occurs in fibrosis, but also the role that epigenetics plays in LOXL2 and cardiovascular disease progression." (PMID 32824630, 2020). "Thus, in the context of cardiovascular diseases, FXa expression in the heart and vasculature can represent a regulatory mechanism for LOXL2." (PMID 37029269, 2023). "Thus, the adult onset of cardiovascular disease noted with neonatal chronic hypoxia is likely related to accelerated arterial stiffening mediated by LOXL2." (PMID 37038896, 2023).
larynx (3 papers, 2014 to 2019). "In patients in whom LOXL2 was not shown to be upregulated, we have to look for other liver-fibrosis pathways." (PMID 31426495, 2019).
cardiac disease (2 papers, 2019 to 2020). "Although there is data linking LOXL2 to fibrosis, its regulation in the fibrotic cardiac disease pathophysiology remains ill-defined, and as such, more research is required to better define LOXL2′s mechanistic role in cardiac tissue fibrosis and subsequent contractile dysfunction." (PMID 32824630, 2020).
hematologic malignancy (2 papers, 2023 to 2025). "An oral LOXL2 inhibitor (GB2064, formerly PAT-1251) is already under clinical evaluation in hematologic malignancy (NCT04679870)." (PMID 41226485, 2025).
infection (2 papers, 2020). The state of being infected such as from the introduction of a foreign agent such as serum, vaccine, antigenic substance or organism. "The high expression of LOXL2 may be associated with the infection of type of HPV A7 and CpG island methylation of genes, which is worthy of further investigation." (PMID 32211324, 2020). "Interestingly, LOXL2 is a secretory protein, and infection of other non-chondrogenic cell types could lead to an anabolic effect due to circulating LOXL2 protein that targets chondrogenic cells." (PMID 33214607, 2020).
metabolic disorder (2 papers, 2022 to 2024). "The results indicated that high‐dose LOXL2 inhibitor alleviated the metabolic disorder caused by D‐gal." (PMID 35712918, 2022).
adenocarcinoma (1 paper, 2020). A common cancer characterized by the presence of malignant glandular cells. "For HPV infection, HPV A7 types were enriched in the high-LOXL2 cluster (P = 0.0145), consistent with the enrichment of HPV A7 type in low-keratin and adenocarcinoma clusters reported in TCGA." (PMID 32211324, 2020).
benign tumors (1 paper, 2008). "LOXL2 showed more than 3-fold increased expression in three MPNSTs, whereas ZNF395 showed approximately similar expression levels in the MPNSTs and the benign tumors." (PMID 18522746, 2008).
neurological disorders (1 paper, 2023). "As of the current state of research, there is no direct evidence linking LOXL2 to neurological disorders or ID." (PMID 37550884, 2023).
LOXL2 also shares sentences with these, for which no sentence is quoted: idiopathic pulmonary fibrosis (10 papers); oral squamous cell carcinoma (4); laryngeal squamous cell carcinoma (3); Alzheimer disease (2); cholestasis (2); Hypertension (2); interstitial lung disease (2); lung squamous cell carcinoma (2); metabolic syndrome (2); non-alcoholic steatohepatitis (2); rheumatoid arthritis (2); schizophrenia (2); Wilson disease (2); aortic aneurysm (1); brain cancer (1); cardiac interstitial fibrosis (1); channelopathies (1); cholangitis (1); chondrosarcoma (1); colitis (1); connective tissue disorder (1); dilated cardiomyopathy (1); End Stage Liver Disease (1); endocervical adenocarcinoma (1); endometrial cancer (1); endothelial dysfunction (1); entropion (1); essential thrombocythemia (1); Ewing sarcoma (1); fatty liver disease (1).
A further 34 diseases each share a sentence with LOXL2 in 1 paper.